SYNGR4 (synaptogyrin 4)
Tractability: Antibody: UniProt predicts a signal peptide or a membrane-spanning region.
Gene: Protein-coding gene on chromosome 19 (48,364,367 to 48,376,377, forward strand). Ensembl gene ENSG00000105467.
Subcellular location: Membrane
Subcellular location (Human Protein Atlas): Golgi apparatus
Gene Ontology:
Cellular component: neuromuscular junction; synaptic vesicle membrane; membrane
Genetic constraint (gnomAD): Loss-of-function variants: 17 observed, 16.32 expected, observed/expected ratio (o/e) 1.04, 90% interval 0.71 to 1.56. The upper end of that interval is the gene's LOEUF score, 1.56, which puts it in group 6 of 6, group 1 being the genes least tolerant of losing a copy. Missense variants: 292 observed, 313.12 expected, observed/expected ratio (o/e) 0.93, 90% interval 0.85 to 1.03. Synonymous variants: 121 observed, 134.39 expected, observed/expected ratio (o/e) 0.9, 90% interval 0.78 to 1.05.
Homologues: Orthologues: chimpanzee SYNGR4 (98% identical), macaque SYNGR4 (92% identical), dog SYNGR4 (80% identical), pig SYNGR4 (75% identical), rat Syngr4 (74% identical), mouse Syngr4 (73% identical), guinea pig SYNGR4 (68% identical), tropical clawed frog syngr4 (30% identical), Caenorhabditis elegans sng-1 (18% identical). Paralogues in human: SYNGR3 (33% identical), SYNGR2 (32% identical), SYNGR1 (31% identical).
Diseases named in the same sentence as SYNGR4 in open-access papers:
SYNGR4 is named in the same sentence as 6 diseases in open-access papers, as found by Europe PMC text mining. Sharing a sentence is not in itself a finding about the gene and the disease. The quoted sentences say what the papers report.
amyotrophic lateral sclerosis (2 papers, 2020 to 2024). Amyotrophic lateral sclerosis (ALS) is a neurodegenerative disease characterized by progressive muscular paralysis reflecting degeneration of motor neurons in the primary motor cortex, corticospinal tracts, brainstem and spinal cord. "SYNGR4 is believed to be the gene responsible for amyotrophic lateral sclerosis, but its involvement in breast cancer remains unclear." (PMID 39902127, 2024). "SYNGR4 is considered to be one of the causative genes for amyotrophic lateral sclerosis, but its role in breast cancer development has not been revealed." (PMID 39902127, 2024).
breast carcinoma (1 paper, 2024). "In this study, we found that reducing SYNGR4 expression leads to a shift in tumor-associated macrophages towards the M1 (pro-inflammatory) phenotype in breast cancer, potentially aiding in the reversal of the anti-inflammatory tumor immune microenvironment." (PMID 39902127, 2024). "SYNGR4 overexpression can affect the prognosis of breast cancer patients by promoting M2 polarization of tumor-associated macrophages in breast cancer, and this molecule may be a novel target for breast cancer immunotherapy." (PMID 39902127, 2024). "Knockdown of SYNGR4 in three breast cancer cell lines using two si-RNAs yielded satisfactory knockdown efficiencies." (PMID 39902127, 2024). "SYNGR4 was found to be upregulated in breast cancer samples, both unpaired and paired, based on data from the TCGA and GTEx pancancer databases." (PMID 39902127, 2024). "The expression of SYNGR4 in a variety of malignancies including breast cancer was analyzed using Genotype Tissue Expression (GTEx) and the Cancer Genome Atlas (TCGA) databases and verified by specimens collected from our center." (PMID 39902127, 2024). "CCK8 assay shows that knockdown of SYNGR4 significantly inhibits the proliferative capacity of various breast cancer cell lines." (PMID 39902127, 2024). "The effect of SYNGR4 on breast cancer prognosis was analyzed using bioinformatics and possible pathways by which this molecule affects breast cancer prognosis were explored." (PMID 39902127, 2024). "Our study revealed that elevated levels of SYNGR4 led to enhanced infiltration of Th2 cells in the immune microenvironment of breast cancer." (PMID 39902127, 2024). "SYNGR4 is highly expressed in a variety of malignant tumors, including breast cancer, and affects the prognosis of breast cancer patients." (PMID 39902127, 2024). "In the pan-cancer analysis, SYNGR4 was overexpressed in 12 malignant tumors including breast cancer." (PMID 39902127, 2024). "SYNGR4 knockdown decreased the malignant characteristics of breast cancer cells, including proliferation and migration, as shown in the clone formation assay." (PMID 39902127, 2024). "In vivo experiments showed that SYNGR4 knockdown breast cancer had reduced tumorigenicity in vivo." (PMID 39902127, 2024). "Overall, SYNGR4 could be a promising target for breast cancer immunotherapy and deserves further investigation." (PMID 39902127, 2024). "We examined how SYNGR4 impacts the outlook for breast cancer by studying its correlation with OS (overall survival) (HR=1.59, P=0.004), DSS (disease specific survival) (HR=1.74, P=0.011), and PFI (progress free interval) (HR=1.64, P=0.003) in patients with breast cancer." (PMID 39902127, 2024). "This network may be a collection of molecular pathways of SYNGR4 affecting breast cancer prognosis." (PMID 39902127, 2024). "The effect of SYNGR4 on immune infiltration of breast cancer was analyzed using GSVA, and the effects of SYNGR4 on breast cancer proliferation, migration, and tumor-associated macrophage polarization in cancer foci were verified by cellular and animal experiments, respectively." (PMID 39902127, 2024).
neurological disease (1 paper, 2024). "Neurological disease network extrapolations revealed genes like Synaptogyrin 4 which is novel in depicting neuronal distress while other proteins of the same family were previously correlated with synaptic plasticity factors under various neurological disease pathology." (PMID 38719902, 2024).
SYNGR4 also shares sentences with these, for which no sentence is quoted: cancer (2 papers); lung adenocarcinoma (1); tumor (1).